TSEN34 (tRNA splicing endonuclease subunit 34)
Description:
Constitutes one of the two catalytic subunit of the tRNA-splicing endonuclease complex, a complex responsible for identification and cleavage of the splice sites in pre-tRNA. It cleaves pre-tRNA at the 5'- and 3'-splice sites to release the intron. The products are an intron and two tRNA half-molecules bearing 2',3'-cyclic phosphate and 5'-OH termini. There are no conserved sequences at the splice sites, but the intron is invariably located at the same site in the gene, placing the splice sites an invariant distance from the constant structural features of the tRNA body. It probably carries the active site for 3'-splice site cleavage. The tRNA splicing endonuclease is also involved in mRNA processing via its association with pre-mRNA 3'-end processing factors, establishing a link between pre-tRNA splicing and pre-mRNA 3'-end formation, suggesting that the endonuclease subunits function in multiple RNA-processing events.
Synonyms: LENG5; SEN34; SEN34L; PCH2C
Tractability: PROTAC: ubiquitination databases record sites on it; its protein half-life has been measured.
Gene: Protein-coding gene on chromosome 19 (54,189,447 to 54,194,538, forward strand). Ensembl gene ENSG00000170892.
Subcellular location: Nucleus; Nucleus, nucleolus
Subcellular location (Human Protein Atlas): Nucleoplasm
Pathways (Reactome):
Metabolism of RNA: tRNA processing in the nucleus
Gene Ontology:
Molecular function: tRNA-intron lyase activity; nucleic acid binding
Biological process: tRNA-type intron splice site recognition and cleavage; tRNA splicing, via endonucleolytic cleavage and ligation
Cellular component: nucleoplasm; tRNA-intron endonuclease complex; nucleolus; nucleus
Genetic constraint (gnomAD): Loss-of-function variants: 25 observed, 30.12 expected, observed/expected ratio (o/e) 0.83, 90% interval 0.6 to 1.16. The upper end of that interval is the gene's LOEUF score, 1.16, which puts it in group 5 of 6, group 1 being the genes least tolerant of losing a copy. Missense variants: 475 observed, 410.89 expected, observed/expected ratio (o/e) 1.16, 90% interval 1.07 to 1.25. Synonymous variants: 209 observed, 176.16 expected, observed/expected ratio (o/e) 1.19, 90% interval 1.06 to 1.33.
Homologues: Orthologues: chimpanzee TSEN34 (97% identical), macaque TSEN34 (95% identical), dog TSEN34 (91% identical), pig TSEN34 (89% identical), rat Tsen34 (89% identical), mouse Tsen34 (88% identical), guinea pig TSEN34 (83% identical), tropical clawed frog tsen34 (40% identical), zebrafish tsen34 (35% identical), Drosophila melanogaster Tsen34 (20% identical), Caenorhabditis elegans tsen-34 (14% identical).
Diseases named in the same sentence as TSEN34 in open-access papers:
TSEN34 is named in the same sentence as 2 diseases in open-access papers, as found by Europe PMC text mining. Sharing a sentence is not in itself a finding about the gene and the disease. The quoted sentences say what the papers report.
pontocerebellar hypoplasia (3 papers, 2017 to 2025). Pontocerebellar hypoplasias (PCH) are a rare heterogeneous group of diseases characterized by hypoplasia and atrophy and/or early neurodegeneration of the cerebellum and pons. "In a cohort of 169 cases of pontocerebellar hypoplasia, 106 were linked to mutations in four genes (TSEN54, TSEN2, TSEN34 and RARS2)." (PMID 28549128, 2017).
TSEN34 also shares sentences with these, for which no sentence is quoted: pontocerebellar hypoplasia type 2C (1 paper).